PPARG (peroxisome proliferator activated receptor gamma)
Diseases named in the same sentence as PPARG in open-access papers (continued):
Sharing a sentence is not in itself a finding about the gene and the disease.
Insulin resistance (continued). "Insulin resistance is related to the adipocyte hormones (leptin and adiponectin) that mediate insulin-sensitizing effects through the activation of adenosine monophosphate dependent kinase (AMPK), PPARγ, and some other signaling pathways." (PMID 34805244, 2021). "Also, Rg3 exerts glucose- and weight-lowering effects by increasing the GLUT4 protein level in skeletal muscle, and the PPARγ protein level and AMPK phosphorylation in the skeletal muscle of obese insulin-resistant rats." (PMID 32161549, 2020). "Moreover, a network framed by PPARγ, NF-κB, and PTP1B signaling pathways crossing with the JNK signaling pathway plays a crucial role in regulating insulin resistance." (PMID 32942585, 2020). "The glucose tolerance tests (GTT) and insulin tolerance tests (ITT) assays showed that the glucose tolerance and insulin resistance were markedly improved, and the expressions of IRS and PPARγ were upregulated in adipose tissue from MIFP1G/P1G mice fed with HFD." (PMID 32265835, 2020). "Moreover, hepatic PPARγ reduces the expression of SOCS-3, which has been suggested to play a crucial role in linking inflammation and hepatic insulin resistance." (PMID 32708786, 2020). "Taken together, we demonstrated that glucose metabolic abnormalities and insulin resistance were developed in IUGR offsprings, in which reduction of GLUT4 expression possibly mediated by suppression of PI3K/Akt signaling via PPARγ-induced PTEN upregulation was involved." (PMID 31071176, 2019). "In contrast, mice without PPARγ in the adipose tissue develop TG accumulation and insulin resistance." (PMID 31208033, 2019). "Wild-type mice lacking the PPARγ gene in the liver exhibited a fat intolerance, increased adiposity and as a result of triglyceride imbalance, developed hyperlipidemia and insulin resistance." (PMID 31121839, 2019). "More recently, it has been reported that phosphorylation at S273 is also facilitated by MEK/ERK, and inhibition of MEK and ERK improves insulin resistance, suggesting that MEK and ERK inhibitors can be therapeutic targets for diabetes through the modulation of PPARγ function." (PMID 30079233, 2018). "Progranulin is positively correlated with insulin resistance, HOMA-IR, and circulating PPARγ." (PMID 30096951, 2018). "This form of post-translational modified PPARγ selectively transactivates target genes involved in insulin resistance, without significant changes in adipogenic or osteogenic gene program." (PMID 30186237, 2018). "Of therapeutic significance, ERK have been shown to phosphorylate PPARγ Ser273 and induce insulin resistance in the absence of Cdk5, rendering ERK as promising anti-diabetic targets." (PMID 30186237, 2018). "Thiazolidinediones (TZDs) are peroxisome proliferator-activated receptor gamma (PPARγ) agonists that lower insulin resistance without directly affecting insulin secretion." (PMID 29379799, 2017). "Through amelioration of metabolic derangement and potential binding of curcumin with peroxisome proliferator-activated receptor gamma (PPAR-γ) as agonist, curcumin could play a preventive role in diet-induced insulin resistance." (PMID 29020971, 2017). "Although dibutyltins display some partial PPARγ/RXRα agonistic effects, the translation of cell-based results assays into in vivo effects on inflammation and insulin resistance is not entirely known." (PMID 28824431, 2017). "Given the pleotropic and important roles of PPARγ in physiology and disease, as well as the wide-spread usage of TZD drugs for the treatment of insulin resistance and type II diabetes, it is of paramount importance to elucidate the mechanisms for how PPARγ and TZDs affect cancer." (PMID 27692066, 2016). "The PPARγ agonist, rosiglitazone, reversed glucose intolerance, but not the insulin resistance in homozygote mice." (PMID 27483259, 2016).
Insulin resistance (continued). "Agonist-induced activation of PPARγ has been demonstrated to increase insulin sensitivity and thiazolidinediones (TZD) are used clinically to reduce insulin resistance and hyperglycemia in patients with type 2 diabetes, although these drugs are also associated with weight gain." (PMID 26317347, 2015). "The development of hepatic steatosis is probably not a consequence of age-dependent insulin resistance as the increased hepatic PPARγ expression is observed as early as 3 months of age in Tg animals (data not shown)." (PMID 26083030, 2015). "Indeed, treatment with thiazolidinediones, synthetic peroxisome proliferator-activated receptor gamma (PPAR-γ) ligands, has been reported to improve insulin resistance partially through increased mitochondrial biogenesis." (PMID 26161384, 2015). "In summary, these findings suggest that PPARγ is involved in EPO/EPOR-induced AKT activation, and targeting the PPARγ/AKT pathway via EPO may have therapeutic implications for hepatic insulin resistance and type 2 diabetes." (PMID 26643367, 2015). "In mice without adiponectin, hepatic insulin resistance was observed in parallel with a decrease in therapeutic response to agonists of PPARγ, indicating that adiponectin is an important factor enhancing PPARγ-mediated improvement in insulin sensitivity." (PMID 24410812, 2014). "As agonists of nuclear receptor peroxisome proliferator-activated receptor gamma (PPAR-γ), thiazolidinediones (TZD) reduce insulin resistance in the liver and peripheral tissues; increase the intake of insulin-dependent glucose and decrease withdrawal of glucose from the liver." (PMID 23945643, 2013). "PPARγ and RBP4 are known to regulate lipid and glucose metabolism and insulin resistance." (PMID 23145084, 2012). "Treatment with C21 ameliorated insulin resistance in KK-Ay mice without influencing blood pressure, at least partially through effects on the PPARγ pathway." (PMID 23155382, 2012). "As already demonstrated, the absence of PPARγ specifically in β-cells cannot fully compensate for the β-cell dysfunction seen in states of peripheral insulin resistance." (PMID 22208362, 2011). "In contrast to the firststudy, here TZDs failed to ameliorate muscle insulin resistance,suggesting that myocyte PPARγ regulates muscle insulinsensitivity cell autonomously." (PMID 17389768, 2007). "In adipose tissue, ROS–FoxO1 signaling suppresses peroxisome proliferator-activated receptor γ (PPARγ) and promotes lipolysis (via adipose triglyceride lipase (ATGL)/hormone-sensitive lipase (HSL)) during fasting, but under overnutrition drives inflammation and insulin resistance via NF-κB/JNK." (PMID 41037185, 2025). "As adipocyte hypertrophy is known as a dominant mechanism of fat cell expansion and enhanced susceptibility to insulin resistance in humans, our results imply a noncanonical function of GSDMD in maintaining adipose tissue plasticity through the regulation of PPARγ." (PMID 36065376, 2022). "This may be due to the deacetylation of Lys268 and Lys293 sites on PPARγ, which can lead to the recruitment of BAT program coactivator Prdm16 to PPARγ, resulting in browning of white adipose tissue and inhibition of genes related to insulin resistance." (PMID 34616289, 2021). "Moreover, PPARG-DM is characterized by insulin resistance, which is not consistent with the phenotype of MODY." (PMID 34764936, 2021). "The main components of EGb may act on multiple targets, such as PTGS2, PPARG, DPP4, and GSK3B, to regulate multiple pathways, and play an antiaging role by inhibiting oxidative stress, inhibiting inflammation, and ameliorating insulin resistance." (PMID 32802136, 2020). "However and not entirely favorable, PPARγ elimination also aggravated the pathological conditions of hyperlipidemia, triglyceride clearance, and muscle insulin resistance." (PMID 31121839, 2019).
Insulin resistance (continued). "Telmisartan, an ARB with strong antihypertensive efficacy, has been shown to activate peroxisome proliferator-activated receptor γ (PPARγ) in non-clinical studies and to improve diabetes-related indices, including insulin resistance, in hypertensive patients with type 2 diabetes mellitus." (PMID 30943275, 2019). "However, it was presumed that the PPARγ activity of PP extract was low, and did not contribute to the improvement of insulin resistance and hyperglycemia." (PMID 30258609, 2018). "Furthermore, we also found that GGQLD regulated lipid aggregation and improved hepatic peroxisome proliferator-activated receptor-gamma (PPAR-γ) and insulin-resistance (IR) expression in vivo and in vitro, further highlighting the anti-inflammatory function of this CHM." (PMID 30671129, 2018). "Activation of PPARγ by TZD leads to increase the storage capacity of fatty acids in the adipocytes and thereby to decrease the amount of circulating fatty acids and ameliorate the insulin resistance, which finally leads to the reduced plasma insulin and glucose levels." (PMID 28690544, 2017). "In our study, CLA group had decreased insulin resistance assessed by HOMA-IR, which might be attributed to energy expenditure, increasing peroxisome proliferators-activated receptor (PPARγ) expression – acting as a ligand for this receptor and adiponectin production." (PMID 27586548, 2016). "However, adipose-specific PPARγ KO mice have insulin resistance in adipose tissue and liver, but not in skeletal muscle when challenged with high-fat diet." (PMID 27483259, 2016). "Our study demonstrates for the first time that PPARγ is essential for EPO-induced improvements in hepatic insulin resistance, which supports the idea that EPO may contribute to a novel strategy for treating insulin resistance and type 2 diabetes." (PMID 26643367, 2015). "In logistic regression models adjusted for each other, or containing age and sex, with and without further adjustment for markers of insulin resistance/sensitivity, neither the IRS1 allele A, nor the PPARG was significantly associated with prevalent type 2 diabetes." (PMID 24447396, 2014). "Furthermore, insulin resistance became more severe in mice lacking macrophage PPARγ following HFD feeding, and these mice were only partially responsive to TZD treatment." (PMID 23577240, 2013). "However, the relationship between PPARγ agonist-increased circulating adiponectin and PPARγ agonist-induced efficacy on insulin resistance has not been studied." (PMID 15491498, 2004). "However PPARg may play a role in β-cell hyperplasia in response to insulin resistance, an idea supported by the fact that mice that lack PPARg in β-cells do not expand their β-cells mass in response to a high-fat diet." (PMID 17465682, 2007). "For example, rosiglitazone dampens the expression of pigment epithelium-derived factor (PEDF), a driver of insulin resistance, in hepatocytes and adipocytes by activating AMP-activated protein kinase (AMPK) rather than PPARγ." (PMID 35392915, 2022). "Adipose-specific PPARγ activation by transgene expression and non-TZD PPARγ agonist (AG035029) treatment prevented insulin resistance equivalent to TZD treatment." (PMID 20814441, 2010). "Lack of PPARγ in this lipoatrophic background protected the mice to develop fatty liver by reducing liver triglyceride and increasing serum FFA levels, but these mice have muscle insulin resistance." (PMID 27483259, 2016). "Collectively, our data indicated that EPO treatment for two to five weeks could upregulate PPARγ to activate the PI3K/AKT pathway and thus alleviate hepatic insulin resistance without inducing hepatic lipid deposition." (PMID 26643367, 2015).
Insulin resistance (continued). "Similarly, C3H mice, which lack Pparγ expression in the liver, did not enhance hepatic Cd36, Fabp4, and Mogat1 expression on the SRD diet or in response to liver insulin perfusions, and furthermore, they did not develop hepatosteatosis and hepatic insulin resistance in response to the SRD." (PMID 26085100, 2015). "Hence, as an FDA-approved clinical drug, CLQ may be a new non-TZD selective PPARγ agonist and further evidence should be provided to establish whether CLQ performs a similar function in the treatment of metabolic diseases, including insulin resistance and hyperglycemia." (PMID 31138783, 2019).
diabetes (878 papers, 2004 to 2026). "Mechanistically, the nuclear receptor PPARγ, previously linked to Metrnl’s insulin-sensitizing effects in diabetes, appears central to this switch." (PMID 41493486, 2026). "In a study investigating atrial fibrosis, activation of PPARγ by pioglitazone can improve the atrial structural and electrophysiological remodeling caused by diabetes." (PMID 41169876, 2025). "Pioglitazone, a peroxisome proliferator-activated receptor gamma (PPAR-γ) agonist also used for diabetes management, is associated with a significant resolution of signs of NASH." (PMID 39199546, 2024). "In the case of PPARG, previous studies have demonstrated that promoter hypermethylation is associated with liver fibrosis, osteoarthritis, diabetes, and atherosclerosis." (PMID 38576768, 2024). "In an attempt to overcome the detrimental effects of diabetes and the associated osteoporosis on the osseointegration of dental implants, PPARγ gene delivery was tried in a diabetes mellitus induced rat model having a lower PPARγ expression." (PMID 38580623, 2024). "GCKR, influencing glucose metabolism, has variations associated with diabetes risk, while PPARG plays a pivotal role in adipogenesis and insulin sensitivity, highlighting its importance in T2DM37,38." (PMID 39020091, 2024). "Studies showed that abnormal expression of PPARγ caused by diet, stress, coronary artery disease, stroke, diabetes, osteoporosis and other factors can increase the risk of depression." (PMID 39247617, 2024). "The PPARG gene represents an excellent bridge between the two types of diabetes: polymorphisms in PPARγ promoter regions contribute to the genetic predisposition to T1D and affect the severity of islet autoimmunity." (PMID 37338602, 2023). "PPARγ antagonists such as betulinic acid have been developed and used in murine models as potential therapies for diabetes which avoid the side-effects associated with PPARγ antagonism." (PMID 36510001, 2023). "Drugs that target peroxisome-proliferator-activated receptor gamma (PPARγ), a protein that controls genes involved in fat storage and fibrosis, have been used to treat diabetes, but can cause unwanted side-effects." (PMID 37886997, 2023). "A clear opportunity for precision diabetes therapy in monogenic IR is offered by the IR and lipodystrophy caused by mutations in PPARG, which encodes the target for thiazolidinediones (TZDs) such as pioglitazone." (PMID 37794082, 2023). "Subsequent studies have identified specific polymorphisms in the PPARG promoter, notably rs10865710 and rs3856806, which are significantly associated with glucose levels in diabetes mellitus patients." (PMID 38201926, 2023). "PPARγ agonists are implicated in the regulation of diabetes and metabolic syndrome and have therapeutic potential in brain disorders." (PMID 35956831, 2022). "When the proportion of CKD patients with diabetes was 100%, PPARG Pro12Ala G was an associate factor for CKD." (PMID 35265101, 2022). "Unfortunately, data on the use of TZDs in individuals with monogenic syndromic form of diabetes caused by LOF mutations in PPARG are still inconclusive." (PMID 35052457, 2022). "In this review, we found commonalities in marker–trait associations of specific genes to diabetes (e.g. PPARG, TCFL2) in specific geographical regions." (PMID 37192883, 2022). "Peroxisome proliferator-activated receptor gamma (PPARγ) has been closely associated with diabetes, menopause, and kidney disease." (PMID 35807748, 2022). "PPARγ is a normal transcriptional regulator which has been reported to be associated with diseases such as diabetes mellitus." (PMID 34336956, 2021). "A first multivariate analysis using the Cox and the CRR model examined all suspected risk factors (sex, age, diabetes, hypercholesterolemia, hypertension, PPARg locus rs2120825) with only age and rs2120825 status being significant." (PMID 33986314, 2021).